GRASLND (glycosaminoglycan regulatory associated long non-coding RNA)
Synonyms: RNF144A-AS1
Gene: Long non-coding RNA gene on chromosome 2 (6,911,754 to 6,918,734, reverse strand). Ensembl gene ENSG00000228203.
Diseases named in the same sentence as GRASLND in open-access papers:
GRASLND is named in the same sentence as 13 diseases in open-access papers, as found by Europe PMC text mining. Sharing a sentence is not in itself a finding about the gene and the disease. The quoted sentences say what the papers report.
bladder cancer (4 papers, 2021 to 2025). "Functional assays of GRASLND in glioma, gastric and bladder cancer, demonstrated an enhancing effect of GRASLND on proliferation, migration and invasion." (PMID 39398277, 2024). "According to some studies RNF144A-AS1, also known as GRASLND, is highly expressed in bladder cancer, and overexpression of the transcript is correlated with poor prognosis." (PMID 34440306, 2021). "Furthermore, GRASLND promotes bladder cancer progression through the miR-455-5p/SOX11 axis." (PMID 39060946, 2024). "Thus far, GRASLND was reported as a prognostic factor in bladder cancer, gastric cancer, glioblastoma, head and neck squamous cell carcinoma, osteosarcoma, and papillary renal cell carcinoma by using bioinformatic pipelines and clinical data from the TCGA database." (PMID 39398277, 2024). "Notably, GRASLND and AC010331.1 have previously been reported as prognostic markers in gastric and bladder cancers, respectively, consistent with our findings." (PMID 40511303, 2025).
melanoma (3 papers, 2024 to 2025). A malignant, usually aggressive tumor composed of atypical, neoplastic melanocytes. "We showed that GRASLND expression is associated with the differentiated, proliferative and non-invasive phenotype in melanoma." (PMID 39398277, 2024). "Based on this and our RNA-Seq results on the IFNγ-associated gene sets, we suspected a suppressor role of GRASLND on IFNγ signaling in melanoma cells." (PMID 39398277, 2024). "Interestingly, GRASLND is overexpressed in differentiated melanomas and associated with poor prognosis." (PMID 39398277, 2024). "The lncRNA GRASLND is upregulated in differentiated cells relative to mesenchymal undifferentiated melanoma cells." (PMID 41463281, 2025). "The exact mechanism by which downregulation of GRASLND promotes melanoma phenotypic switch demands deeper clarification." (PMID 39398277, 2024). "We conclude, that the discrepancy of the observed phenotypes after GRASLND knockdown regarding melanoma cell invasiveness can be attributed to their different cell states." (PMID 39398277, 2024). "We propose that melanoma cells upregulate GRASLND to inhibit this pathway and thus evade immune cell recognition." (PMID 39398277, 2024). "Despite lncRNA’s tissue- and cell type-specificity, we found an immune-relevant role of GRASLND in suppressing the IFNγ signaling in melanoma, and thus influencing the HLA-I-APM." (PMID 39398277, 2024). "Given its identification as a key regulator in mesenchymal stem cells (MSCs), where it suppresses IFNγ signaling and considering its emerging role in cancer biology, we investigated the function of lncRNA GRASLND in the context of melanoma." (PMID 39398277, 2024). "The discovery of GRASLND’s upregulation in melanoma and its impact on phenotypic switching, along with affected pathways, point towards potential clinical relevance." (PMID 39398277, 2024). "Our findings revealed GRASLND’s cell state-dependent function as a suppressor of the invasive and dedifferentiated melanoma phenotype and demonstrated that this lncRNA is dominantly expressed in differentiated, melanocytic melanoma cells." (PMID 39398277, 2024). "The human melanoma cell line 501-mel was selected as a differentiated, melanocytic cell model exhibiting the significantly highest GRASLND expression among all tested cell lines." (PMID 39398277, 2024). "In sum, the transcriptomic data confirm a role for GRASLND in melanoma differentiation, as its downregulation induces switching towards a dedifferentiated, highly invasive cell state and points towards potentially critically pathways involved." (PMID 39398277, 2024). "Our findings demonstrate that in differentiated melanomas elevated expression of GRASLND interferes with anti-tumor effects of IFNγ, suggesting a role of GRASLND in tumor immune evasion." (PMID 39398277, 2024). "In line, GRASLND is inversely correlated with RTK AXL, having a Spearman coefficient of −0.80 (p = 1.8 × 10−8), supporting our findings of a correlation between GRASLND expression and the melanoma cell state." (PMID 39398277, 2024). "Clinical data analysis from melanoma patients unveiled enrichment of GRASLND in immunologically ‘cold tumors’ characterized by reduced immune infiltrates and lower response to immune checkpoint inhibitors (ICIs)." (PMID 39398277, 2024). "A recent study suggested that GRASLND has pro-tumorigenic activity by enhancing YAP1 signaling in melanoma, thereby promoting its tumorigenicity." (PMID 39398277, 2024). "To validate this, we analyzed human melanoma patient data from the TCGA database grouped by their tumoral GRASLND expression with regard to the overall survival." (PMID 39398277, 2024). "To further validate the two molecules screened in the prescreening, we first assessed the expression level of GRASLND in melanoma and normal tissues by qRT–PCR, and the results showed that its expression was significantly upregulated in SKCM." (PMID 39060946, 2024).
melanoma (continued). "Taken together, these observations suggest the involvement of GRASLND in controlling melanoma plasticity." (PMID 39398277, 2024). "In conclusion, our work on lncRNA GRASLND in melanoma revealed its function as a barrier to the invasive EMT-like phenotypic switch and an association with a differentiated and proliferative melanoma cell state." (PMID 39398277, 2024). "GRASLND knockdown revealed switching of differentiated, melanocytic melanoma cells towards a dedifferentiated, slow-proliferating and highly-invasive cell state." (PMID 39398277, 2024). "To investigate the role of lncRNA GRASLND in melanoma, we generated doxycycline-inducible knockdown cell lines using two small hairpin RNAs (shGRAS1 and shGRAS2) and a non-targeting control shRNA (shCtr)." (PMID 39398277, 2024). "In this study, we investigated lncRNA GRASLND in the melanoma context." (PMID 39398277, 2024). "In sum, our findings support the hypothesis that GRASLND inhibits IFNγ signaling in melanoma, suggesting an immune evasion mechanism of melanoma cells by upregulating lncRNA GRASLND." (PMID 39398277, 2024). "Also congruent with these earlier reports in various cancer types, including melanoma, we noted that GRASLND facilitated cell proliferation." (PMID 39398277, 2024). "Here, we show a relevance of lncRNA GRASLND in melanoma differentiation and IFNγ signaling." (PMID 39398277, 2024). "However, in contrast to recent findings that showed GRASLND enhances the invasion ability in certain intermediate state melanoma cell lines, our research indicates it suppresses the invasive potential of differentiated melanoma cells." (PMID 39398277, 2024). "Recognizing the role of melanoma cell differentiation status in therapy resistance and tumor aggressiveness, we first aimed to examine whether GRASLND expression varies depending on cell state." (PMID 39398277, 2024). "Therefore, we determined the expression of GRASLND lncRNA across nine melanoma cell lines." (PMID 39398277, 2024). "STAT3 antagonizes MITF and drives melanoma metastasis in vivo suggesting a potential STAT3-mediated dedifferentiation in response to GRASLND downregulation." (PMID 39398277, 2024). "Overall, these findings demonstrated that GRASLND knockdown induced a transition to a non-proliferative melanoma cell state without inducing cell death." (PMID 39398277, 2024). "GRASLND knockdown induced a phenotypic switch from a proliferative, less invasive and differentiated melanoma cell state towards a non-proliferative, highly invasive and dedifferentiated state." (PMID 39398277, 2024). "GRASLND knockdown promoted the non-proliferative state of melanoma cells." (PMID 41463281, 2025). "Interestingly, all differentiated melanoma cell lines, such as 501-mel, SK-MEL-239, Ma-Mel-86c and Ma-Mel-61a, expressed significantly higher GRASLND levels in contrast to all dedifferentiated, mesenchymal-like and AXLhigh cell lines SK-MEL-147, C8161, WM1361a and Ma-Mel-86a." (PMID 39398277, 2024). "This indicates that GRASLND’s negative impact on patient survival is probably a result of its adverse effects on tumor immunogenicity and its role as a potential immune evasion mechanism in melanoma patients." (PMID 39398277, 2024). "Our findings suggest that GRASLND is a potential marker for prognostic and immunotherapeutic response determination in SKCM patients, and an in-depth study of its functional mechanism may provide new targets and therapeutic strategies for melanoma immunotherapy." (PMID 39060946, 2024).
gastric cancer (2 papers, 2024). A primary or metastatic malignant neoplasm involving the stomach. "Previous studies have indicated that GRASLND serves as an unfavourable prognostic marker in several cancer types, due to the promotion of cell proliferation, migration and invasion in glioma, bladder and gastric cancer." (PMID 39398277, 2024). "Increased expression of GRASLND in gastric cancer tissues has been reported to promote tumor metastasis and proliferation by targeting the miR-30c-2-3p/LOX axis, suggesting a strong correlation between GRASLND, poor prognosis, and advanced disease in SKCM patients." (PMID 39060946, 2024).
skin cutaneous melanoma (2 papers, 2024). "The lncRNA GRASLND functions as an oncogene in many cancers, but its role in skin cutaneous melanoma (SKCM) requires further investigation." (PMID 39060946, 2024). "In addition, the expression level of GRASLND in skin cutaneous melanoma (SKCM-TCGA, n = 471) is significantly higher (mean Log2FC = 4.56, p = 3 × 10−153) than in normal skin tissues (GTEx database, n = 701), indicating a pathological relevance in this malignancy." (PMID 39398277, 2024).
osteoarthritis (1 paper, 2020). A noninflammatory degenerative joint disease occurring chiefly in older persons, characterized by degeneration of the articular cartilage, hypertrophy of bone at the margins and changes in the synovial membrane. "Our results indicate an important role of GRASLND in regulating stem cell chondrogenesis, as well as its therapeutic potential in the treatment of cartilage-related diseases, such as osteoarthritis." (PMID 32202492, 2020). "Therefore, we proposed that GRASLND may possess some therapeutic potential through suppression of IFN signaling in osteoarthritis." (PMID 32202492, 2020).
viral infection (1 paper, 2020). "Since lentivirus was used to manipulate the expression of GRASLND, it is possible that our observations were confounded by the cellular response to viral infection." (PMID 32202492, 2020).
cancer (3 papers, 2021 to 2024). A tumor composed of atypical neoplastic, often pleomorphic cells that invade other tissues. "Among the lncRNAs in our cancer-related signature, RNF144A-AS1, now called GRASLND, was reported to serve as an important regulator in stem cell chondrogenesis." (PMID 34663322, 2021).
tumor (3 papers, 2023 to 2024). "We also found mutual inhibition of GRASLND and miR-218-5p expression, suggesting that GRASLND has a miR-218-5p-mediated tumor suppressor effect on SKCM cells." (PMID 39060946, 2024). "Nevertheless, we found a negative association of GRASLND expression and tumor immunosurveillance." (PMID 39398277, 2024). "Thus, we concluded that GRASLND is an immune-related lncRNA that is of clinical relevance and may contribute to tumor immune evasion." (PMID 39398277, 2024).
GRASLND also shares sentences with these, for which no sentence is quoted: glioblastoma (1 paper); glioma (1); head and neck squamous cell carcinoma (1); osteosarcoma (1); papillary renal cell carcinoma (1).